CDK1 (cyclin dependent kinase 1)
Diseases named in the same sentence as CDK1 in open-access papers (continued):
Sharing a sentence is not in itself a finding about the gene and the disease.
tumor (continued). "In conclusion, our study showed, as the first time, CHPF as a tumor promotor for MM, whose function was carried out probably through the regulation of CDK1." (PMID 32612115, 2020). "Accordingly, the protein expression of CDK1 detected by IHC in TMA verified the upregulated expression of CDK1 in tumor tissues compared with normal skin tissues, which was similar with the manner of CHPF." (PMID 32612115, 2020). "More recent literature on β-TrCP, however, suggests that this protein indeed suppressed tumor progression, as one study showed that β-TrCP regulates the degradation of CDK1, high levels of which promote certain aspects of tumor malignancy." (PMID 32605588, 2020). "Severe knock‐down of CDK1 (shCDK1#1) caused rapid cell death (Fig EV5C and D) and moderate CDK1 silencing (shCDK1#2) significantly impaired cell proliferation, tumor sphere formation, and clonogenic capacities of T24 BC cells." (PMID 31709755, 2020). "Previous investigators have shown that dysregulation of CDK1 leads to G2 phase arrest and promotes tumor progression, making it an ideal biomarker and therapeutic target." (PMID 33224872, 2020). "Here, we examined the expressions of p‐CDC25C, CDC25C, p‐CDK1, CDK1, and cyclinB1 in tumor tissues from mice with different treatments by western bolt." (PMID 32780562, 2020). "Anti-CDK1 treatment can boost sorafenib antitumor responses in HCC patient-derived xenograft (PDX) tumor models." (PMID 32746792, 2020). "In vitro and in vivo detection demonstrated that CHPF acts as a tumor promoter in MM, probably through the regulation of CDK1." (PMID 32612115, 2020). "CDKN1A is a tumor suppressor that mainly functions as a cell cycle checkpoint by binding to CDK1, Cyclin‐dependent kinase 2 (CDK2), or the CDK4/6 complex." (PMID 33037696, 2020). "On the other hand, LMNA down‐regulates the expression of P16 (the tumour suppressor gene), resulting in the up‐regulation of CDK1." (PMID 32896989, 2020). "MiR-582-5p has tumor-suppressive functions and reduces the tumor cell proliferation and migration via targeting CDK1, FOXC1, and RAB27a." (PMID 33183321, 2020). "CR8 was shown to target similar Cdks as Roscovitine including Cdk1, Cdk2, Cdk5, Cdk7 and Cdk9, but with much stronger efficacy and a predicted improved anti-tumor potential." (PMID 32380742, 2020). "In summary, we have shown that phosphorylation of TFCP2L1 at Thr177 by CDK1 is important for ESC pluripotency and cell cycle processes, and that its aberrant activation in adult bladder tissue is associated with tumor progression and poor prognosis of BC." (PMID 31709755, 2020). "CDK1 expression is upregulated in liver samples from HCC patients in comparison to non-tumor tissues." (PMID 32018226, 2020). "For example, Anaphase-Promoting Complex or Cyclosome (APC/C) is an E3 ubiquitin ligase and functions as a tumor suppressor by degrading CDKs, whereas high expression of CDK1 was previously reported to be correlated with poor survival." (PMID 32785169, 2020). "BITC induced G2 arrest and apoptosis, decreasing tumor growth in nude mice by downregulation of cyclin B1 and Cdk1 expression." (PMID 33263014, 2020). "In conclusion, the up-regulation of BUB1B, CCNA2, CDC20, CDK1, and WEE1 in tumor tissues are associated with worse OS and DFS in PDAC and is correlated with advanced tumor stage and tumor development." (PMID 30765611, 2019). "This analysis confirmed the connection of INPP4B with ER status, CDK1 with tumor grade, and ERBB2 with HER2 status." (PMID 31315058, 2019). "Since curcumin strongly modified CDK1 and 2 as well as Cyclin A and B in all tumor cell lines, the physiologic relevance of these proteins was evaluated by siRNA knock-down." (PMID 30909499, 2019).
tumor (continued). "The C-terminal acidic domain (CAD) of TSPX is crucial for the tumor suppressor functions, such as inhibition of cyclin B/CDK1 phosphorylation and androgen receptor transactivation." (PMID 30863497, 2019). "The three key proteins identified by our decision tree are strongly associated with important clinical parameters, namely ER status (INPP4B), tumor grade (CDK1), and HER2 status (ERBB2)." (PMID 31315058, 2019). "PTEN loss results in activation of AKT, CDK1, and CDK2 kinases, which in turn leads to phosphorylation of FOXO1, exclusion of FOXO1 from the nucleus, and loss of the tumor suppressor functions in the nucleus 18, 25-27." (PMID 31410199, 2019). "This signaling, which affects the cell proliferation through P21 and CDK1, results in an antiproliferative effect to the tumor cells." (PMID 31024941, 2019). "Accordingly, a Western blot analysis was performed on these extracted tumor tissues, and it demonstrated a remarkable decrease of both CDK1 expression in the dinaciclib group, confirming the preceding results (P < 0.05)." (PMID 31207099, 2019). "CDK1 is a member of the Ser/Thr protein kinase family that is frequently overexpressed in HCC and associated with tumor progression." (PMID 30891079, 2019). "Proteins that contribute most strongly to the proteotype-based classification include INPP4B, CDK1, and ERBB2 and are associated with estrogen receptor (ER) status, tumor grade status, and HER2 status." (PMID 31315058, 2019). "PTEN loss leads to AKT- and CDK1- or CDK2-mediated phosphorylation of FOXO1, exclusion of FOXO1 protein from the nucleus, and loss of its tumor suppressor functions in the nucleus 18, 25-27." (PMID 31410199, 2019). "The second of our key proteins, mitotic kinase CDK1, is known to accelerate critical processes required for mitosis and correlates with tumor grade." (PMID 31315058, 2019). "The mechanism by which high levels of brachyury decrease the expression of CDK1 protein was previously identified as a reduction of CDK1 protein stability in brachyury-high tumor cells." (PMID 29774202, 2018). "CDK1 is essential for cell cycle and its overexpression is directly correlated with the clinical features such as tumor stage and therapy outcome." (PMID 29484121, 2018). "The CDK1/2/9 inhibitor AZD5438 had superior anti-tumor activity in two models with higher copy number of CCNE1." (PMID 29433585, 2018). "AZD5438, a CDK1/2/9 inhibitor, has shown potent antiproliferative activity in a range of tumor cells." (PMID 29433585, 2018). "Our previous studies showed that α-pinene reduces the expression of cyclinB1 and CDK1 proteins in tumor tissue." (PMID 30473536, 2018). "For example, PBK/TOPK is upregulated during the cytogenesis of tumor cells, most likely by phosphorylation of Thr9 and activation by cyclin B1/cdk1." (PMID 30286126, 2018). "Response gene to complement-32 (RGC-32) activates cyclin-dependent kinase 1, regulates the cell cycle and is deregulated in many human tumours." (PMID 29385536, 2018). "CDKN1A (cyclin-dependent kinase inhibitor 1A; also known as p21, Cip1, Waf1) is a tumor suppressor that regulates cell proliferation and binds to and inhibits kinase activity of Cdk2 and Cdk1, leading to cell cycle arrest." (PMID 30514244, 2018). "Immunohistochemical analysis of tumour tissues from the nude mice demonstrated significant induction of CDK1 expression in the DLEU1 transfection group compared to the control group (P < 0.05)." (PMID 28598010, 2017). "Since we have revealed that the expression of CDK1 and iASPP at mRNA and protein levels were both increased in tumor tissues; suppressing CDK1 and iASPP expression in tumor tissues present a promising strategy for CRC treatment." (PMID 29069733, 2017). "Results showed that CDK1 and iASPP protein levels in tumor tissues were significantly increased, compared to normal tissues." (PMID 29069733, 2017).
tumor (continued). "Results showed that in LV-sh-XIST infected mouse tumor, CDK1 and Cyclin D1 protein levels were reduced, whereas P21 protein level was increased, compared with LV-sh-contr infected mouse tumor." (PMID 29371940, 2017). "As Cdk1 inhibitors effectively arrested tumor cell growth, finding the new Cdk1 inhibitors is a new target in the research and development of anticancer drugs." (PMID 29250124, 2017). "This analysis underscored canonical tumor promoting genes (e.g. cell cycle promoting genes such as CDK1 and BUB1) that were up-regulated in LUADs relative to normal lung tissues and concomitantly downstream of down-regulated TBX2 with the same gene-network." (PMID 28978111, 2017). "The protein levels of CDK1 and iASPP in tumor tissues and adjacent normal tissues were determined using Western blot assays." (PMID 29069733, 2017). "Multivariate Cox analyses showed that CDK1 level, tumor size, and satellite nodule status were independent prognostic factors for the OS of HCC patients." (PMID 28434945, 2017). "For the CDK1 gene, the analyzed tags (203213_at and 203214_x_) indicated higher expression of the CDK1 gene in all analyzed cell lines, tumor samples, and controls." (PMID 26912061, 2016). "The influence of SFN on Caki-1res differed from that on Caki-1par in as much as total and activated Cdk1 and Cdk2 were elevated in the everolimus-resistant tumor cells." (PMID 27863441, 2016). "Consistent with a proposed switch in the AR driven transcriptional program with local tumour progression, we observed a consistent increase in the expression of a number of these genes in higher-grade tumours, particularly CDK1, UBE2C, CDC20 and CCNA2." (PMID 27120785, 2016). "Our study demonstrates that dinaciclib, a serine/threonine kinase inhibitor against CDK1, 2, 5, and 9, inhibited tumor growth in TNBC PDXs and cell line models in vitro and in vivo, by arresting cells in the G2-M phase and inducing apoptosis." (PMID 27486754, 2016). "We demonstrated that inhibition of CDK1 or cyclin B1 by RNAi to reduced tumor cell proliferation in TNBC." (PMID 27486754, 2016). "DNA methylation level of CDK1 gene promoter was analyzed in all cell lines and primary tumor samples." (PMID 26912061, 2016). "Our study identifies novel cooperative mechanisms involving PIP5K1α, AR-V7, CDK1 and AR, which drive tumor progression and contribute to enzalutamide resistance." (PMID 27588408, 2016). "Taken together, our study identifies novel cooperative mechanisms involving PIP5K1α, AR-V7, CDK1 and AR, which drive tumor progression and contribute to enzalutamide resistance." (PMID 27588408, 2016). "Cdk1 as well as CCNB1 expression were readily detectable in all embryonal tumor cell lines investigated." (PMID 26029996, 2015). "In the results of our study, CDK1 protein was expressed in 52 of 77 OSCCs (67.5%), as compared with 21 of 60 controlled epithelia adjacent to the tumours (35.0%, P<0.01)." (PMID 25129248, 2015). "It is well known that cdk1 is overexpressed in a variety of tumor entities including prostate cancer and oral squamous cell carcinoma." (PMID 26029996, 2015). "To summarize, RAD001 added to sunitinib-sensitive tumour cells reduced cdk1 and up-regulated p19 and p27." (PMID 25444514, 2015). "The sunitinib-resistant tumour cell response to sorafenib was different from the control cell response, in as much as cdk1 and cdk2 were elevated and p27 was reduced over controls in Caki-1 cells." (PMID 25444514, 2015). "Mechanistically, high levels of cdk1 promote tumor growth by stabilizing HIF1α and contribute to neoplastic transformation by phosphorylation of YAP." (PMID 26029996, 2015).
tumor (continued). "Of the 9 patients who had tumor recurrence, only one was found in Group B. Supervised analysis showed decreased kinase activity of CDK1 and RSK1-4 substrates in those which progressed compared to others." (PMID 26406598, 2015). "Further investigation of these effects in in vivo models is warranted to evaluate the efficacy of targeting cdk1 as a novel tool in tumor therapy." (PMID 26029996, 2015). "There was a significant difference in CDK1 expression between epithelia adjacent to the tumours and OSCC." (PMID 25129248, 2015). "CDK1 expression correlated with the occurrence of the tumor local recurrence, and the regional lymph node metastasis." (PMID 25129248, 2015). "Previous studies had demonstrated that Dinaciclib was a CDK1/2/5/9 inhibitor leading to tumor apoptosis." (PMID 25045703, 2014). "When targeting tumor progression, inhibition of both lipid and protein tyrosine kinases has shown promise; similarly, dual inhibition of the Aurora A and CDK1 kinases targets multiple critical stages in the cell cycle." (PMID 25393739, 2014). "A similar analysis in BRCA1 vs BRCA2 tumours highlighted increase in PPI co-expression around the mitotic regulators CDK1, CDC20 and CKS1B and the histone deacetylases HDAC1 and HDAC6; these are known drug targets for which inhibitors have been developed." (PMID 25521701, 2014). "MiR-21 promotes tumor cell proliferation by inhibiting PDCD4 (programmed cell death protein 4), a tumor suppressor that prevents cell cycle progression via activation of the cyclin-dependent kinase 1 (Cdk1) inhibitor p21." (PMID 24275848, 2013). "Sites on CMGC kinases dominated the list of most frequently identified tumor sites including CDK1 Tyr15, and the activation loop sites on p38 MAPK, PRP4, ERK1, ERK2, and GSK-3." (PMID 24260357, 2013). "In some cells, Cdk1 has shown an anti-proliferative effect, and indeed it has been classified as a tumour suppressor, while in hematopoietic cells, Cdk6 is very abundant and essential for proliferation." (PMID 24312219, 2013). "For investigation, a lethal concentration of cinnamaldehydes (80 μM for CA, 30 μM for BCA, FHCA and FBCA) that led G2 arrested HCT 116 cells to cell death was selected to examine the possible effects on cdk1 in relation to induction of tumor cell death." (PMID 23185555, 2012). "Aberrant activity of cyclin B1/Cdk1 is found in the radiation-derived tumor resistance, and inhibition of cyclin B1/Cdk1 activity enhances tumor radiosensitivity by increasing apoptosis." (PMID 20808790, 2010). "In this study, we investigated the influence of indirubin and derivatives on CDK1/cyclin B kinase in human tumour cells at concentrations known to induce growth inhibition." (PMID 11161389, 2001). "A composite SRSF11 × CDK1 × TERT signature may enhance the precision of tumor classification, particularly in HCC and CRC, where these splicing networks converge." (PMID 41584036, 2026). "A systematic analysis showed that the expression of CDK1 is related to multiple immunomodulator and chemokine expression and increased infiltration of numerous immune cells, which could reshape the tumor immune microenvironment." (PMID 40040723, 2025). "Moreover, single-cell RNA-seq data revealed that CDK1 is preferentially expressed in proliferating T cells and M1 macrophages, reinforcing its possible role in immune regulation and tumor-host interactions." (PMID 41278293, 2025).
tumor (continued). "CDK1 not only plays a role in cell cycle regulation, but may also influence immune cell infiltration and activity in the tumor microenvironment." (PMID 40332418, 2025). "Database-based screening combined with molecular docking simulations identifies API as a specific CDK1 inhibitor reversing NiNP-induced FAM dysregulation and tumor progression, clarifying NiNPs’ oncogenic potential and proposing a CDK1/FAM-targeted LUAD therapy with natural compounds." (PMID 41226659, 2025). "Using immune infiltration analysis, we observed a significant association of CDK1 expression with the infiltration pattern of immune cells in the tumor microenvironment, suggesting that CDK1 may affect tumor growth and spread by regulating the immune response." (PMID 40332418, 2025). "By integrating bioinformatics analyses, IHC staining of patient tissues, and in vitro functional studies, we demonstrated that PLCH1 promoted tumor cell proliferation and survival by regulating cell cycle proteins (CDK1 and Cyclin B1) and the ERK-EGR1 signaling pathway." (PMID 40519297, 2025). "In contrast, the AS/BJO-NEs may exert its anti-tumor effects by regulating CDK1 and down-regulating MTFR2, thereby inhibiting OSCC EMT and associated processes." (PMID 40748969, 2025). "Furthermore, cdk1 has been shown to influence tumor progression by inducing a dysregulation of the cell cycle." (PMID 40282352, 2025). "Furthermore, CDK1 plays a role in regulating immune tolerance, tumor spread, and cell growth and diversification." (PMID 39991589, 2025). "Notably, CDCA3 was found to interact with CDK1, and CDK1 overexpression negated the tumor-suppressive effects of CDCA3 downregulation." (PMID 40969596, 2025). "This further supports the potential role of CDK1 in regulating anti-tumor immune responses." (PMID 41278293, 2025). "CDK1 activity is rarely deregulated in cancer and is required for tumor formation." (PMID 40486867, 2025). "Additionally, multiple studies [,49,50] have shown that downregulating CDK1 can arrest the tumor cell cycle and inhibit tumorigenesis, development, and the EMT process." (PMID 40748969, 2025). "Additionally, CDK1 promotes tumor development and enhances drug resistance by influencing cell morphology, motility, and apoptosis." (PMID 40181976, 2025). "CDK1, a master regulator of the cell cycle, is frequently overexpressed in metastatic cervical, breast, and neuroblastoma cancers, where it drives G2/M transition and tumor proliferation." (PMID 41244050, 2025). "Based on these data, we inferred that Con-A + SB-treated cells had significantly lower expression levels of proteins linked to tumor formation, such as JAK1, STAT3, PCNA, cyclin D1, along with evidence of G2/M phase arrest, as indicated by the downregulation of Cyclin B and Cdk1." (PMID 40350446, 2025). "The interaction of SPAG5 with key hub genes such as MDM2 and CDK1 not only reinforces its role in tumour suppression through negative regulation but also highlights its potential in moderating the phenotypic and genomic alterations associated with AML progression." (PMID 39762615, 2025). "As a key factor in cell cycle regulation, CDK1 has a regulatory effect on the tumor immune microenvironment, and its abnormal expression may affect the proliferation and apoptosis of HCC cells." (PMID 40332418, 2025). "Inhibitors of CDK1 can arrest the cell cycle, thereby inhibiting tumor cell proliferation." (PMID 40170854, 2025). "Beyond its canonical role in cell cycle progression, CDK1 may also participate in other crucial pathways, including DNA damage repair and modulation of the tumor immune microenvironment." (PMID 41278293, 2025). "Detecting CDK1 peptide in tissues and organs could be of great help in the early diagnosis of tumours." (PMID 40710305, 2025). "With tumor progression to the metaphase, the expression level of CDK1 increased significantly, suggesting that CDK1 may be involved in the malignant progression of HCC." (PMID 40332418, 2025).